UCA1 (urothelial cancer associated 1)
Diseases named in the same sentence as UCA1 in open-access papers (continued):
Sharing a sentence is not in itself a finding about the gene and the disease.
glioma (continued). "SiRNA against Dicer, which is necessary for miRNA biogenesis, was cotransfected with UCA1 siRNA in glioma cells, and we found that knockdown of Dicer attenuated or even reversed the inhibition of UCA1 siRNA on Slug expression." (PMID 30410864, 2018). "UCA1-regulated malignant behaviors of glioma cells by binding to its direct target miR-627-5p, which was confirmed to function as a tumor suppressor in glioma cells." (PMID 30518750, 2018). "As expected, knockdown of UCA1 attenuated the EMT process in glioma cells characterized as an increase of the epithelial maker E‐cadherin expression, and decrease of the mesenchymal marker Slug expression." (PMID 30410864, 2018). "As expected, knockdown of UCA1 attenuated the promotive effects of TGF‐β on the EMT process in glioma cells." (PMID 30410864, 2018). "This study demonstrated that the NR2C2-uORF impaired the pivotal roles that UCA1-miR-627-5p-NR2C2 feedback loop had in regulating the malignancies of glioma cells by targeting NR2C2 directly." (PMID 30518750, 2018). "By upregulating zinc finger E-box binding homeobox 1 (ZEB1), UCA1 could sponge miR-204-5p to stimulate glioma cell motility, invasion, and EMT." (PMID 39170516, 2024). "UCA1 could promote glioma cell proliferation and cell cycle in adults through the up-regulation of cyclin D1 transcription." (PMID 37444408, 2023). "Notably, TGF-β treatment in glioma cells significantly increases the expression of lncRNA UCA1; knockdown of UCA1 decreases Slug expression by releasing the inhibitory activity of miR-1 and miR-203, which are competitively bound by this lncRNA." (PMID 37239035, 2023). "UCA1/miR-182/PFKFB2 axis could modify GBM-associated stromal cells-mediated glycolysis and invasion of glioma cells." (PMID 34178658, 2021). "Besides, lncRNA UCA1 regulates glioma growth and metastasis via miR- 182-dependent regulation of iASPP protein." (PMID 33080570, 2020). "For example, UCA1 accelerated the growth of glioma cells by decreasing miR-182 to target iASPP." (PMID 32883232, 2020). "UCA1 may be a potential therapeutic target for glioma treatment, though further studies are required to thoroughly understand the mechanisms of UCA1 in glioma development." (PMID 31596734, 2019). "The present study only determined the interaction between UCA1 and Wnt/β-catenin signaling pathway, and future studies may explore if UCA1 also affect other signaling pathways to regulate glioma progression." (PMID 31596734, 2019). "In addition, UCA1 can interact with miR-182 to modulate glioma proliferation and migration by targetting iASPP." (PMID 30940776, 2019). "Moreover, miR-182 directly binds to fructose-2,6-biphosphatase; thus, the UCA1/miR-182 axis thereby modulates GASC-induced glycolysis in glioma cells." (PMID 31014014, 2019). "LncRNA UCA1 was identified as a pivotal regulator for tumorigenesis of glioma." (PMID 31798345, 2019). "Collectively, these results suggested the oncogenic role of UCA1 in the glioma progression." (PMID 31596734, 2019). "It revealed that the down-regulation of UCA1 inhibited glioma cell migration and invasion." (PMID 31798345, 2019). "In addition, the in vivo tumor growth shows that UCA1 knockdown repressed glioma growth in vivo, but CLOCK expression was suppressed in tumor tissues." (PMID 31798345, 2019). "UCA1 could promote the proliferation and cell cycle of glioma cells via the up-regulating of cyclin D1 transcription." (PMID 31798345, 2019). "The present study employed the xenograft nude mice model to determine the in vivo effects of UCA1, and further study may use the orthotopic glioma models to further confirm our findings." (PMID 31596734, 2019). "In our study, we demonstrated that knock-down of UCA1 suppressed the activities of Wnt/β-catenin signaling in the glioma cells, and more importantly overexpression of UCA1 also increased the activities of Wnt/β-catenin signaling in the tumor tissues isolated from the nude mice." (PMID 31596734, 2019).
glioma (continued). "Notably, CXCL14-high GASCs mediated lncRNA UCA1 upregulation and miR-182 downregulation in glioma cells." (PMID 31014014, 2019). "More importantly, the knock-down of UCA1 in U87 and SH139 cells also decreased the IC50 of cisplatin as compared to cells transfected with scramble siRNA, and LiCl treatment restored the inhibitory effect of UCA1 siRNA transfection on glioma cell chemo-resistance." (PMID 31596734, 2019). "More importantly, high expression of UCA1 predicted poor clinical outcome in glioma patients." (PMID 31596734, 2019). "Previous researches showed that UCA1 could sponge miR-122 and promoted glioma cell progression, migration, and invasion." (PMID 31798345, 2019). "The clinical samples from patients with glioma were collected for the analysis of UCA1 by qRT-PCR." (PMID 31596734, 2019). "Overall, the results demonstrated that UCA1/miR-206/CLOCK axis participated in the progressing of glioma and could act as a promising therapeutic target." (PMID 31798345, 2019). "He demonstrated that the knockdown of UCA1 suppressed glioma cell proliferation and migration." (PMID 31798345, 2019). "LncRNA UCA1 was up-regulated in glioma cell lines and tissues." (PMID 31798345, 2019). "The expression of UCA1 in glioma cells were normalized to that of human astrocytes." (PMID 31596734, 2019). "The role of UCA1 in glioma was investigated in the present study." (PMID 31596734, 2019). "The monolayer system was used throughout the in vitro studies, and the effects of UCA1 on the spheroidic glioma cell progression may be a future direction of our study." (PMID 31596734, 2019). "However, the expression and biological activities of UCA1 in its association with miR-206 and other related RNAs (CLOCK), especially the combinational axis in the functions of glioma, are not fully known." (PMID 31798345, 2019). "In our study, the up-regulation of UCA1 was correlated with poor survival in patients with glioma." (PMID 31596734, 2019). "It has been reported that UCA1 was closely related to glioma." (PMID 31798345, 2019). "However, minimal researchers have discovered the full associations of UCA1, miR-206, and the CLOCK gene in glioma tumor." (PMID 31798345, 2019). "Our present study found that UCA1 is overexpressed in glioma cells and tissues." (PMID 30518750, 2018). "Additionally, TGF‐β induced EMT and the stemness of glioma cells, whereas knockdown of lncRNA UCA1 attenuated these two processes and their enhancement by TGF‐β." (PMID 30410864, 2018). "Although more details should be clarified, we strongly believe the TGF‐β–UCA1–Slug regulatory axis plays important roles in regulating the stemness and EMT in glioma cells, and lncRNA UCA1 might be a potential target for glioma treatment or prognosis." (PMID 30410864, 2018). "We found that lncRNA UCA1 expression was induced by TGF‐β in glioma cells." (PMID 30410864, 2018). "In addition, the enhancement of the stemness of glioma cells mediated by TGF‐β was abrogated by UCA1 knockdown, evident by the rescue of sphere formation, ALDH1 activity and the expression of stemness markers." (PMID 30410864, 2018). "Notably, ceRNA activity of UCA1 in glioma cells has been indicated in the previous studies; for example, UCA1 targets miR‐122 to promote proliferation, migration and invasion of glioma cells." (PMID 30410864, 2018). "In our study, we demonstrated that UCA1 expression was promoted in glioma tissues and cells." (PMID 30518750, 2018). "Furthermore, the attenuation of UCA1 knockdown on the stemness of glioma cells was abrogated by Slug ectopic expression, evident by recovery of the capacity of cell spheroid formation, ALDH1 activity and the expression of stemness markers (ALDH1 and Nanog)." (PMID 30410864, 2018). "This study confirmed that lnc-UCA1 was up-regulated in glioma tissues and cells." (PMID 30518750, 2018).
glioma (continued). "Then, glioma cells were transfected with miR‐1 or miR‐203a mimics or inhibitor, and qRT‐PCR results showed that overexpression of miR‐1 or miR‐203a significantly decreased UCA1 expression, while transfection of their inhibitors increased UCA1 expression." (PMID 30410864, 2018). "We defined miR-627-5p as a novel target of UCA1 and our results confirmed the significant interaction between UCA1 and miR-627-5p in the process of tumorigenesis, that is UCA1 knockdown impaired the malignant behaviors of glioma cells by promoting miR-627-5p expression." (PMID 30518750, 2018). "To test our speculation, RNA‐FISH was performed to evaluate the localization of miR‐1, miR‐203a and UCA1 in glioma tissues; we found that both miR‐1 and miR‐203a were colocalized with UCA1 in cytoplasm of glioma cells." (PMID 30410864, 2018). "We further compared the expression of UCA1 in different groups of patients based on the tumor grade and found that the expression of UCA1 was positively correlated with the tumor grade, i.e. the more advance tumor grade, and higher expression level of UCA1 in the glioma tissues (P<0.05)." (PMID 31596734, 2019). "But the impact that UCA1 may have on glioma remained unclear." (PMID 30518750, 2018). "Notably, the expression of lncRNA UCA1 and Slug was positively correlated in glioma tissues." (PMID 30410864, 2018). "Eventually, we had confirmed that lncRNA UCA1 could act as a ceRNA for Slug in glioma cells." (PMID 30410864, 2018). "We further investigated whether lncRNA UCA1 was involved in TGF‐β‐induced effects in glioma cells." (PMID 30410864, 2018). "In glioma, TGF-β-regulated lncRNAs lncRNA-ATB, UCA1, LINC00645, and LINC00115 modulate proliferation, invasion, and glioma stem cell renewal." (PMID 35223453, 2021). "Several studies have demonstrated that UCA1 promotes cell proliferation and EMT in osteosarcoma, glioma and papillary thyroid carcinoma by activating the Wnt/β-catenin signaling pathway." (PMID 33777227, 2021). "Previous studies have shown that some lncRNAs, such as TUG1, UCA1, and AFAP1-AS1, regulated the expression of miR-145 by a sponging mechanism in glioma stem cells (GSCs), nasopharyngeal carcinoma (NPC) cell lines, and OSCC cell lines, respectively." (PMID 34946098, 2021). "This study will discuss the expression of UCA1 regarding miR-206 and CLOCK, and their integrative effects on the progressing and cell cycle of glioma." (PMID 31798345, 2019). "The axis of UCA1/miR-206/CLOCK was a valid prognostic indicator and a new therapeutic method for glioma." (PMID 31798345, 2019). "In order to further confirm that the role of UCA1 in glioma cell invasion and migration involved in Wnt/β-catenin signaling, we treated the U87 and SHG139 cells with both UCA1 siRNA and LiCl (GSK3β inhibitor, which activates the Wnt/β-catenin signaling)." (PMID 31596734, 2019). "Our experiments, results, and analysis indicated that UCA1 enhanced cell growth and invasion through the miR-206/CLOCK axis in glioma." (PMID 31798345, 2019). "The growth of glioma tumors was suppressed by the silencing of UCA1 in vivo, and the expression of CLOCK protein was also significantly lowered by the knockdown of UCA1." (PMID 31798345, 2019). "Long noncoding RNAs (lncRNAs) were proved to be critical regulators in the tumorigenesis of glioma, such as CCAT1, ZEB1-AS1, TUG1, and UCA1." (PMID 31798345, 2019). "This study will discuss the expression of UCA1 regarding miR-206 and CLOCK, and their integrative effects in the proliferation and cell cycle of glioma cells." (PMID 31798345, 2019). "In this study, we first examined the expression levels of uORF, UCA1, miR-627-5p, and NR2C2 in glioma tissues and cell lines." (PMID 30518750, 2018). "In the present study, we showed that TGF‐β induced the expression of lncRNA UCA1, and promoted EMT and the stemness of glioma cells in a concentration‐dependent manner, and that this effect was rescued by UCA1 knockdown." (PMID 30410864, 2018).
glioma (continued). "Our results suggest that lncRNA UCA1 is responsible for TGF‐β‐induced promotion of the EMT and stemness of glioma cells." (PMID 30410864, 2018). "Based on these results, the interaction among UCA1, miR-627-5p, and NR2C2 in regulating malignant behaviors of gliomas, as well as the role of NR2C2-uORF in this pathway were also explored." (PMID 30518750, 2018). "Knockdown of UCA1 inactivates the MAPK signaling pathway by downregulating CDK6 expression mediated by miR-193a, which decreases the proliferation and promotes the apoptosis of glioma cells." (PMID 33777227, 2021). "The results demonstrated that the axis of UCA1/miR-206/CLOCK could modulate the cell proliferation of glioma cells and the growth of glioma tumors." (PMID 31798345, 2019). "Moreover, UCA1, regulating CC M6, M17, and PFC M6, has been identified as a pivotal regulator in the tumorigenesis of glioma which represent the most common solid tumor of childhood." (PMID 31649562, 2019). "The expression of UCA1 in glioma tissues were significantly higher than that in adjacent normal brain tissues (P<0.05)." (PMID 31596734, 2019). "After characterizing the roles of UCA1, miR-206, CLOCK in glioma cells and tissues in vitro, we hope to know whether UCA1 may pose an effect on the glioma growth in vivo." (PMID 31798345, 2019). "Interestingly, GASCs expressing high levels of CXCL14 have been shown to upregulate lncRNA UCA1 and downregulate miR-182, with miR-182 directly binding to PFKFB2 to modulate CXCL14 secretion, glycolysis, and the invasion of glioma cells." (PMID 30234009, 2018). "Importantly, overexpression of Slug abrogated the attenuation of UCA1 knockdown on the EMT and stemness of glioma cells, and their expression exhibited a positive correlation in glioma tissues." (PMID 30410864, 2018). "Notably, ectopic expression of Slug rescued the attenuation of UCA1 knockdown on EMT and the stemness of glioma cells." (PMID 30410864, 2018). "Hence, these results suggest that lncRNA UCA1 attenuates EMT and the stemness of glioma cells dependent on expression of Slug, the downstream effector of TGF‐β signaling." (PMID 30410864, 2018). "Furthermore, lncRNA UCA1 interacts with miR-204 via a negative impacting mechanism, resulting in glioma progression by glioma cell migration and proliferation via downregulation of anti-miR-182 protein." (PMID 37245177, 2023). "Notably, UCA1 competitively binds with miR-1 and miR-203a to upregulate the expression of Slug, a downstream effector of TGF-β, and subsequently regulates EMT in glioma cells and BC cells." (PMID 33777227, 2021). "This evidence indicated that the expression of CLOCK was closely related to miR-206 and UCA1, which may pose a negative effect on the development of glioma." (PMID 31798345, 2019). "Importantly, RIP analysis indicated that both miR‐1 and miR‐203a levels were enriched in RNA pulled down by ago2 in glioma cells transfected with Luc‐UCA1‐wt, but not in cells with Luc‐UCA1‐mut‐1 or Luc‐UCA1‐mut‐203a transfection." (PMID 30410864, 2018). "Moreover, the luciferase activity of Luc‐Slug‐3′UTR was increased in glioma cells cotransfected with Luc‐UCA1‐wt, Luc‐UCA1‐mut‐1 or Luc‐UCA1‐mut‐203a, rather than with Luc‐UCA1‐mut." (PMID 30410864, 2018). "Therefore, our results demonstrate that lncRNA UCA1 could indeed promote the EMT and stemness of glioma cells." (PMID 30410864, 2018). "However, while these genes have been described to be expressed in glioma, we found the transcriptional levels of WNT6 are not significantly correlated with CAV1 (r = −0.03, P = 0.66) or PLAGL2 (r = 0.07, P = 0.36) in human GBM, and UCA1 and WNT6 are inversely correlated (r = −0.29, P < 0.001)." (PMID 31923345, 2020). "However, in the clinical follow-up study, we have not examined whether UCA1 expression in glioma tissues was correlated with the chemo-sensitivity in patients with glioma, and further studies have to be conducted to address this concern." (PMID 31596734, 2019).
glioma (continued). "The long non‐coding RNA (lncRNA) UCA1 has been shown to promote the proliferation and invasion of cervical cancer cells through regulating miR‐206 expression, but the involvement of UCA1 in regulating the stemness and epithelial–mesenchymal transition (EMT) of glioma cells is unknown." (PMID 30410864, 2018). "TGF-β induces the expression of several lncRNAs (LINC00645, LINC00115, UCA1, lnc-ATB) through the canonical or non-canonical signaling pathway to promote glioma progression." (PMID 35223453, 2021). "However, the roles and related mechanisms of UCA1 in regulating the stemness and epithelial–mesenchymal transition (EMT) of glioma cells have not been revealed." (PMID 30410864, 2018).